CXCL8 (C-X-C motif chemokine ligand 8)
Diseases named in the same sentence as CXCL8 in open-access papers (continued):
Sharing a sentence is not in itself a finding about the gene and the disease.
infection (continued). "Interleukin-8 (IL-8, CXCL8) is a pro-inflammatory chemokine produced by various cell types to recruit leukocytes to sites of infection or tissue injury." (PMID 27348007, 2016). "As regulators of inflammation, monocytes are able to produce pro-inflammatory mediators such as IL-8 (CXCL8), a chemokine that controls the influx of inflammatory and immune cells to sites of injury and infection, and IL-6, a key B cell differentiation factor." (PMID 27391120, 2016). "Neutrophils are recruited to sites of infection in response to chemokines of the Cys-Xxx-Cys chemokine family, such as IL-8 (CXCL8)." (PMID 28066767, 2016). "The importance of the level of inflammation is highlighted by the strong correlation between the levels of CXCL8 in rectal fluids 2 weeks before SIVmac239wt challenge and the plasma VLs 2 weeks post-SIVmac239wt infection." (PMID 26886938, 2016). "Taken together these studies underscore the importance of infection and inflammation in contributing to the exaggerated expression of CXCL8 in the CF lung." (PMID 26140537, 2015). "Rig-1, Mda5, and Tlr3 are involved in the host immune response to DTMUV, and the expression of proinflammatory cytokines (Il-1β, –2, –6, Cxcl8) and antiviral proteins (Mx, Oas, etc.)are also upregulated early in infection." (PMID 26005441, 2015). "As a result, local γδ T cells expand and release chemokines such as CXCL8 (IL8) which then recruits further neutrophils to the site of infection." (PMID 26539557, 2015). "Based on microarray analyses, expression of cytokines and chemokines such as CCL20 and CXCL8 was shown to be increased upon E. coli 1303 infection 514 and 58-fold, respectively." (PMID 26062913, 2015). "CXCL8 is an important signaling chemokine which is secreted in copious amounts by monocytes in response to infection and it serves to recruit neutrophils to the site of infection along a chemotactic gradient." (PMID 25037882, 2014). "Our results show that CXCL8 mediates productive infection of HIV-1 in MDM and microglia via receptors CXCR1 and CXCR2." (PMID 24662979, 2014). "Upon contact with fungi, airway epithelial cells produce large amounts of cytokines and chemokines, such as the prototypic interleukin 8 (CXCL8), which recruit leukocytes to the pulmonary site of infection to enhance antifungal host defense activities." (PMID 24735832, 2014). "The present study investigated the effect of CXCL8 on productive infection of HIV-1 in human monocytes-derived macrophages (MDM) and primary human microglia." (PMID 24662979, 2014). "In contrast, treatment with these drugs inhibited TNFα secretion with or without infection, and budesonide or combination of budesonide and formoterol inhibited CXCL8 secretion after infection." (PMID 24219422, 2013). "Protein levels of CCL2 and CXCL8 were measured in supernatants from infected macrophages harvested at 16 h post-infection by ELISAs." (PMID 23265239, 2013). "The secretion of CXCL8 and IL-6 from infected epithelial cells was delayed and began 24 h of infection." (PMID 22058091, 2012). "To confirm the results for the mRNA expression, we studied the protein secretion of cytokine IL6 and chemokine CXCL8 by ELISA at 24 h after the infection." (PMID 22277078, 2012). "The basal level of CXCL8 in control samples was 295 pg/ml, which increased to 1354 pg/ml upon infection." (PMID 22045866, 2012). "IL-8 (CXCL8) is an important activator of the host immune response to Mtb by recruiting inflammatory cells to the site of infection." (PMID 22570668, 2012). "Severe infection demands immediate response and would result in higher levels of CXCL8 expression, and is best represented by profiles seen for the 10 μg dose." (PMID 20668677, 2010). "Changes in levels of transcripts encoding CCL3 (MIP1-α), CXCL8 (swine IL-8), and IL-1β were found to be very close to that indicated by SAGE with all declining as the infection progressed." (PMID 22331987, 2010).
infection (continued). "At the earliest stage of infection, microbial products activate local macrophages and tissue cells to produce neutrophil-specific (CXCL8 and related chemokines) and monocyte/γδ T cell-specific chemokines (CCL2-5)." (PMID 19229322, 2009). "After the initial decrease in CXCL8 levels in both groups of animals, the levels normalized to pre-infection levels." (PMID 20011586, 2009). "In viewof the importance of IL-13, or of the shared receptor between IL-4and IL-13, our data do not allow us to exclude the possibilitythat IL-4 synergizes with IL-13 to downregulate CXCL-8 productionduring infection with M. bovis BCG." (PMID 16864907, 2006). "Pro-inflammatory TNFα, CCL2 and CXCL8 are important in maintaining a balance between recruitment of other macrophages and also T cells to restrict infection." (PMID 16001981, 2005). "Considering the crucial role of the syk-binding motif in CXCL8 induction, we demonstrated that EV-D68 infection could increase AKT phosphorylation at Ser473." (PMID 39962077, 2025). "CXCL8 integrates into early inflammatory networks during infection establishment." (PMID 40642274, 2025). "Infections, requiring both NF-κB and AP-1 activation for CXCL8 gene transcription." (PMID 41344087, 2025). "However, the secretion of TNF-α, IL-6, and CXCL-8/IL-8 by DENV-2-infected MDMs occurred at late stages of infection, suggesting that the translation and/or secretion of these inflammatory factors are delayed in DENV-2 replicative cycle." (PMID 40934228, 2025). "Stimulation of both primary monocytes and THP-1 reporter cell lines with SARS-CoV-2-derived ssRNA led to profound upregulation of all measured cytokine genes, while primary monocytes increased TNF, IL1B and IL6 and decreased CXCL8 expression upon infection with replication-competent SARS-CoV-2." (PMID 39963132, 2025). "Similarly, production of CXCL8, a chemokine that activates γδT cells and neutrophils to combat infection, is lower in preterm infants with low GA or suspected infection." (PMID 40788119, 2025). "Therefore, we further assessed the amount of secreted CXCL8 protein in the cell supernatant following infection with EV-D68 at MOIs of 0.03 or 0.12." (PMID 39962077, 2025). "In addition, macrophages secrete chemokines (e.g., CCL2 and CXCL8) to attract other immune cells (e.g., neutrophils and T cells) to the site of infection, further enhancing immune defense." (PMID 39949625, 2025). "Consistent with this, it has been shown previously that the presence of AA enhanced the release of IL-6 and CXCL-8 (IL-8) during RV16 infection of a human respiratory epithelial cell line (Beas-2B);45 however, changes in the lipid membrane profile as well as viral replication were not analyzed." (PMID 38179897, 2024). "Matching the data collected during the physical characterization of the NTHi-NHNE infection, expression levels of key chemo- and cytokines (e.g. CXCL8, IL-6, IL-1β, CCL3, CXCL1 & CXCL2) and genes involved in ECM remodelling and inflammation (PLAU, Serpine1, MMP9) increased further on day14." (PMID 38990812, 2024). "CXCL8, also called IL-8, is a chemotactic factor involved in the inflammatory response by attracting neutrophils, basophils, and T cells to eliminate pathogens and protect the host from infection, whereas IL1B is a potent proinflammatory cytokine." (PMID 38920854, 2024). "CXCL8 is expressed by various ocular surface cell types, including corneal and conjunctival epithelial cells, corneal keratocytes, PMNs, and macrophages, in response to the infection." (PMID 38694515, 2024). "CXCL8 serves as a crucial chemokine for attracting neutrophils during infection." (PMID 38742103, 2024). "Neutrophils are recruited to sites of infection by inflammatory cytokines, particularly the chemokine CXCL8 [murine homologues are keratinocyte chemoattractant (KC) and macrophage-inflammatory protein 2 (MIP-2)], which binds CXCR1 and CXCR2 receptors on neutrophils." (PMID 39015565, 2024).
infection (continued). "CXCL1, CXCL2 and CXCL8 produce a local inflammatory response when infection or injury occurs." (PMID 39656442, 2024). "One hundred fifty-seven differentially expressed cellular proteins were identified, including 84 upregulated and 73 downregulated proteins at 48 h post-infection, among which CXCL8, DDX3X, and TRPV2 may play crucial roles in viral propagation." (PMID 39772141, 2024). "The ability of Deer-RECs to downregulate CXCL8 and TNF expression early may be key to their ability to weather the cytokine storm associated with SARS-CoV-2 WA1/2020 infection." (PMID 38189329, 2024). "In addition, alveolar macrophages are capable of recruiting a large influx of neutrophils to the lower airways in more severe infections by generating neutrophil-recruiting chemokines such as CXCL8 and leukotriene B4." (PMID 37180449, 2023). "We used qPCR to analyze 12 host-related genes, including those with no significant fold change (IL12A), modest (e.g. TNF, LMO1, IL10, CCL2, IL1B) or high fold change, including CXCL8 which was among the 50 identified to be most significantly dysregulated in monocytes as a result of infection." (PMID 36747074, 2023). "Moreover, neonates born to mothers with recent or ongoing infection express higher plasma levels of IL-10 and CXCL8 than their paired mothers." (PMID 37242334, 2023). "CXCL8 functions as a chemotactic factor by guiding the neutrophils to the site of infection." (PMID 37183243, 2023). "However, at 24 h of infection with persister cells, a bi-modal trend was present in IL-6 and CXCL-8 with an overall increase in secretion, compared to 1.5 h, while IL-10 was at levels identical to uninfected macrophages." (PMID 36920189, 2023). "Importantly, the induction kinetics of IL-6 and CXCL8 post-infection are consistent at the mRNA and protein levels in our study, which further strengthens the robustness of our data." (PMID 37112842, 2023). "Infection of PBECs led to induction of CXCL8, interleukin (IL)-1β, IL-6 and TNF." (PMID 37180449, 2023). "The most common chemokines in comparison tend to be CXC-motif chemokine 2/keratinocyte-derived chemokine (CXCL2/KC) and CXC-motif chemokine 8/interleukin-8 (CXCL8/IL-8), which control the recruitment of neutrophils as T-cells to sites of infection/inflammation." (PMID 35806229, 2022). "Our meta-analysis of randomized trials suggests that short-term inhibition of CXCL8 activity improved survival in patients at high risk for in-hospital mortality without increasing the risk of infection." (PMID 35958623, 2022). "Similarly, high expression of CXCL8 also promotes the recruitment of neutrophils to the site of infection." (PMID 36059536, 2022). "CXCL8 acts as a chemokine by directing neutrophils to the site of infection." (PMID 36120307, 2022). "The chemokine CXCL8, also known as interleukin-8 (IL-8), is initially known as a cytokine expressed by epithelial cells and macrophages for neutrophil recruitment to areas of inflammation, infection, or injury." (PMID 35372515, 2022). "Released CXCL8 could recruit the neutrophil aggregation in tissues/organs which suffered by injury, infection, or inflammation." (PMID 36062083, 2022). "Venn diagram analysis showed that among the common DGEs in the 3 h and 12 h infection groups compared with the control group, 11 differential genes were enriched in the NF-κB signaling pathway, including CXCL8, IL-1β, CCL4, IκBα, TNF, NF-κB, CFLAR, PTGS2, TRAF1, PLAU, and IL-1β2." (PMID 35215890, 2022). "In vitro, in cell lines and primary bronchial epithelial cells, pre-incubation with NTHi followed by infection with RV results in upregulation of the neutrophil chemoattractants CXCL8 (IL-8), epithelial-derived neutrophil-activating peptide 78 (CXCL5) and growth-related oncogene α (CXCL1)." (PMID 36130784, 2022). "However, GEE analyses revealed a marked acceleration of the infection-induced responses measured as the amount of CXCL-8 and CXCL-10 on d3 and d6." (PMID 34959949, 2021).
infection (continued). "It has been reported that the infection with SARS-CoV-2 can cause a cytokine storm in patients with symptoms severe or critical, consisting of an increase of IL-1β, IL-4, IL-6, IL-10, IL-17, TNF-α, G-CSF, GM-CSF, IFN-γ, CCL2, CXCL8, and CXCL10." (PMID 33917837, 2021). "In addition, ASFV-CN/GS/2018 infection is involved in the regulation of chemokine expression in PAMs, such as CXCL8 and CXCL10." (PMID 34412678, 2021). "In addition, pDCs also upregulated the expression of IL-6 and CXCL8 during infection by either ZIKV or DENV compared to pDCs in mock-infected samples." (PMID 34160241, 2021). "In addition, infant AMφs produced significantly more CXCL8 (q = 0.007) in culture supernatants at 24 h post-infection, but significantly less CXCL9 (q = 0.007) compared with adult AMφs." (PMID 32265931, 2020). "An important chemokine in infection and inflammation is CXCL-8/IL-8." (PMID 32581816, 2020). "We found an increase in CXCL-8 at both time points of infection." (PMID 33253325, 2020). "CXCL8 is a chemokine secreted by PMNs to stimulate a variety of pro-inflammatory innate immune responses, including phagocytosis, chemotaxis, and recruitment of additional PMNs to the site of infection." (PMID 33143710, 2020). "Additionally, upon infection, pulmonary epithelium and lung fibroblasts produce chemokine (C-X-C motif) ligand 8 (CXCL8), which promotes the rapid recruitment of neutrophils." (PMID 31888124, 2019). "Interestingly, in occult mf negative O. volvulus infections, serum levels of pro-inflammatory chemokines MCP-1, MIP-1α, MIP-1β, MPIF-1 and CXCL8 were also enhanced in comparison to sera from infection-free controls." (PMID 31525197, 2019). "This differential modulation of CXCL10 and CXCL8/IL8 may suggest a different role of both chemokines in the infection." (PMID 31619718, 2019). "Also, immature DCs produce CXCL8 to promote neutrophil migration into the site of infection or vaccination." (PMID 30742635, 2019). "Interestingly, TNF-α was shown to have an inhibitory effect on the secretion of CXCL8 in the first 24 h post-infection (hpi)." (PMID 31331089, 2019). "Infection of PBECs with RV induced an increase in CXCL8 mRNA and protein secretion." (PMID 30333178, 2019). "Therefore, CXCL8-GAG interactions must be highly tuned for coordinated neutrophil recruitment to the insult site for successful resolution of infection." (PMID 30115951, 2018). "Furthermore, significantly reduced IL-6, CCL20, and hBD2 expression along with CXCL8 and CCL20 secretion by RHE were observed at 16 h post-infection using T3SS deficient strain." (PMID 30070169, 2018). "Culminating in an enhanced CXCL8 release, this might be beneficial to create a pro-inflammatory environment in order to mount an immune response, eventually clearing the infection by recruitment of neutrophils." (PMID 28740179, 2017). "CXCL8/IL-8 is also a key chemokine, which is not only involved in the generation hyper-inflammatory responses but also triggers leukocyte recruitment to the infection sites." (PMID 28484461, 2017). "In our study we sampled CXCL8 levels at 5 days post-infection in median." (PMID 27802348, 2016). "By contrast, the gene expression of CXCL8 was also strongly induced, however, a significant increase in the gene expression could only be detected 30 h post-infection." (PMID 27310007, 2016). "CXCL8 is a proinflammatory chemokine involved in the neutrophils chemotaxis after infection." (PMID 26859141, 2016). "However, infection with the organism led to the secretion of relatively high concentrations of CXCL8." (PMID 27002636, 2016). "In order to determine whether active bacterial growth is essential for CXCL8 production in W. chondrophila infected cells, HEp2 cells were treated with the antibiotic chloramphenicol 2 hours post-infection with live W. chondrophila (MOI 10)." (PMID 27002636, 2016).
infection (continued). "In addition, infection is strongly associated with increased transcription from a number of cytokine and chemokine genes, including IL1A and CXCL8 (IL-8), that contribute to recruitment of new neutrophil hosts, and to inflammatory tissue injury and disease." (PMID 27703927, 2016). "Finally, we demonstrate that neutrophils are recruited to the infection site through the inflammasome-independent production of CXCL8 and LTB4 where they then mediate bacterial clearance through the Gbp4 inflammasome-dependent biosynthesis of PGs." (PMID 27363812, 2016). "Immune cells, including neutrophils, are recruited to the site of infection by chemokines such as CXCL8 (Interleukin-8) and CCL3 (macrophage inhibitory protein-1alpha-MIP1α) and other inflammatory stimuli including the bacteria-derived N-formyl-methionyl-leucyl-phenylalanine (fMLP)." (PMID 25360483, 2015). "When the infection persists, CXCL8 expression correlates with the severity of inflammation." (PMID 24646914, 2014). "BAL HNP 1–3 and CXCL8/IL‐8 were increased during infection (P = 0.003 and P = 0.011, respectively)." (PMID 24673807, 2014). "Therefore, the effects of W. chondrophila infection upon the expression of the pro-inflammatory cytokines, TNF-α, IL-1α, IL-1β and the chemokine CXCL8 was investigated 24 h post-infection." (PMID 25010668, 2014). "Previous studies, utilizing the zebrafish model system, have shown that Cxcr2 receptor signaling axis is involved in both long-range systemic neutrophil mobilization from hematopoietic tissue as well as local recruitment to infection or purified Cxcl8 (IL-8, a potent Cxcr2 ligand)." (PMID 25372289, 2014). "mRNA levels for CXCL8 in cells and CXCL8 protein in cell supernatants were both reduced following Benin 97/1 infection compared to either mock-infection or infection with OURT88/3 isolate providing support for reduced levels of functional CXCL8 in supernatants from Benin 97/1 infected cells." (PMID 23265239, 2013). "CXCL8 is a potent inflammation marker recruiting neutrophils to sites of infection." (PMID 23181472, 2012). "Endothelial cells secrete the neutrophil chemokine CXCL8 upon infection." (PMID 22045866, 2012). "CXCL-8/IL-8 is the main tissue-derived chemoattractant for neutrophils; however, our observations demonstrated that the bovine IL-8 response did not always parallel the somatic cell response during the different S. aureus intramammary infections." (PMID 21884610, 2011). "However, infection with T. carassii also significantly induced CXCL8_L2 (a chemokine related to mammalian IL-8,) in spleen leukocytes." (PMID 20885956, 2010). "This conclusion is supported, at least in part, by the results of Sukumaran and colleagues, who reported the upregulated expression of chemokine genes encoding CXCL1, CXCL2, CXCL3, CXCL8, CCL3, CCL4 and CCL20 after infection of PMN with Anaplasma phagocytophilum." (PMID 17875202, 2007). "The question is whether pre-infection of the NPTr, PAMs and BM-DCs with mycoplasmas and then infection with S. suis increases the expression of two important pro-inflammatory cytokines, IL-6 and CXCL8." (PMID 37513713, 2023). "Genes encoding CXCL1 (GRO1) and CXCL8 (IL-8) showed the highest changes in expression in cells infected with the NADL (cp) strain, which in the case of CXCL8 was confirmed by RT-qPCR, while the chemokine signaling pathway was enriched by genes with increased expression 72 h after infection." (PMID 35746747, 2022).